BMPER (BMP binding endothelial regulator)
Description:
Inhibitor of bone morphogenetic protein (BMP) function, it may regulate BMP responsiveness of osteoblasts and chondrocytes.
Synonyms: Cv2; CRIM3; CV-2
Tractability: Antibody: UniProt places it where antibodies can reach, with high confidence; UniProt predicts a signal peptide or a membrane-spanning region; its Gene Ontology location is reachable by antibodies, with medium confidence.
Safety:
Unwanted effects reported when the protein is acted on. In parentheses: how it was acted on, where the effect was seen, and who reports it.
creatinine clearance (source: ClinPGx)
Gene: Protein-coding gene on chromosome 7 (33,904,308 to 34,156,427, forward strand). Ensembl gene ENSG00000164619.
Subcellular location: Secreted
Gene Ontology:
Molecular function: extracellular matrix structural constituent
Biological process: blood vessel endothelial cell proliferation involved in sprouting angiogenesis; endothelial cell activation; positive regulation of ERK1 and ERK2 cascade; positive regulation of SMAD protein signal transduction; positive regulation of sprouting angiogenesis; regulation of endothelial cell migration; blood vessel development; regulation of angiogenesis; BMP signaling pathway; regulation of protein localization; regulation of transmembrane receptor protein serine/threonine kinase signaling pathway; SMAD protein signal transduction; system development; tube development; ureteric bud development
Cellular component: extracellular region; extracellular matrix; non-collagenous component of interstitial matrix
Genetic constraint (gnomAD): Loss-of-function variants: 45 observed, 88.55 expected, observed/expected ratio (o/e) 0.51, 90% interval 0.4 to 0.65. The upper end of that interval is the gene's LOEUF score, 0.65, which puts it in group 2 of 6, group 1 being the genes least tolerant of losing a copy. Missense variants: 756 observed, 882.08 expected, observed/expected ratio (o/e) 0.86, 90% interval 0.81 to 0.91. Synonymous variants: 316 observed, 325.05 expected, observed/expected ratio (o/e) 0.97, 90% interval 0.89 to 1.07.
Homologues: Orthologues: chimpanzee BMPER (99% identical), macaque BMPER (99% identical), rabbit BMPER (96% identical), pig BMPER (94% identical), rat Bmper (93% identical), mouse Bmper (93% identical), dog BMPER (91% identical), guinea pig Bmper (83% identical), tropical clawed frog bmper (80% identical), zebrafish bmper (65% identical). Paralogues in human: MUC5AC (29% identical), MUC5B (29% identical), FCGBP (28% identical), OTOGL (27% identical), MUC2 (27% identical), VWF (27% identical), OTOG (26% identical), MUC6 (26% identical), TECTA (25% identical), ZAN (25% identical), MUC19 (24% identical), KCP (19% identical), and 7 more.
Diseases named in the same sentence as BMPER in open-access papers:
BMPER is named in the same sentence as 58 diseases in open-access papers, as found by Europe PMC text mining. Sharing a sentence is not in itself a finding about the gene and the disease. The quoted sentences say what the papers report.
diaphanospondylodysostosis (8 papers, 2015 to 2023). Diaphanospondylodysostosis is characterized by absent ossification of the vertebral bodies and sacrum associated with variable anomalies. "Homozygous and compound heterozygous pathogenic variants in BMPER (BMP binding endothelial regulator) cause diaphanospondylodysostosis and ischiospinal dysostosis, likely variable manifestations of the same skeletal dysplasia." (PMID 35627201, 2022). "Bone morphogenetic protein-binding endothelial cell precursor-derived regulator (BMPER) gene mutation presents a disease spectrum ranging from a mild type of ischiospinal dysostosis (ISD) to a more severe type of diaphanospondylodysostosis (DSD)." (PMID 35328179, 2022). "BMPER mutations cause skeletal disorders such as Diaphanospondylodysostosis (DSD), with phenotypic similarities to the BMPER-null mouse, and the milder Ischiospinal dysostosis." (PMID 30125619, 2019). "Additionally, mutations in human BMPER have been associated with the lethal skeletal disorder diaphanospondylodysostosis." (PMID 36799927, 2023). "ISD is similar to, but milder than the lethal/semilethal condition termed diaphanospondylodysostosis (DSD), which is associated with homozygous or compound heterozygous mutations of bone morphogenetic protein-binding endothelial regulator protein (BMPER) gene." (PMID 26728142, 2016).
Obesity (5 papers, 2019 to 2025). Accumulation of substantial excess body fat. "If BMPER inhibited the effects of BMP-9 in vivo, one would expect the opposite outcome after BMPER overexpression, i.e., increased obesity and enhanced susceptibility to diabetes." (PMID 41378712, 2025). "BMPs play a role in obesity through regulating adipogenesis and energy storage partitioning, we asked whether BMPER also regulates body weight through modulating BMP signaling." (PMID 33772019, 2021). "Accordingly, we found that genes related to angiogenesis (e.g., ANGPT1, ANXA2), as well as to TGFβ signaling (e.g., SMAD4, BMPER, AKT2) are modulated in obesity condition." (PMID 30838002, 2019). "We now reveal that BMPER marks both adipose progenitors as well as mature adipocytes in human omental fat and mouse perigonadal fat independent of sex and obesity." (PMID 37311809, 2023). "However, the role of BMPER in obesity and insulin resistance has not been studied before." (PMID 33772019, 2021).
diabetes (4 papers, 2015 to 2025). "We also tested whether BMPER alleviates insulin resistance in a Leprdb/db (db/db) monogenic mouse model of severe diabetes." (PMID 33772019, 2021). "Our data reveal that BMPER is a protective regulator of glucose homeostasis and could become a potential therapeutic target for treating diabetes." (PMID 33772019, 2021). "We conclude that BMPER exhibits therapeutic potential for the treatment of diabetes." (PMID 33772019, 2021).
idiopathic pulmonary fibrosis (4 papers, 2015 to 2024). Idiopathic pulmonary fibrosis (IPF) is a nonneoplastic pulmonary disease that is characterized by the formation of scar tissue within the lungs in the absence of any known cause. "Additional studies are required to gain the mechanisms that cause BMPER promoter be methylated and whether BMPER promoter only is sufficient to induce lung fibrosis." (PMID 26442443, 2015). "Treatment with 5-aza-dC can reduce BMPER expression in fibroblasts and mitigate invasion and migration of idiopathic pulmonary fibrosis lung fibroblasts." (PMID 38244582, 2024). "BMPER, as a regulator of BMP signaling, is implicated in blood vessel development, vascular inflammation, HSC maturation and lung fibrosis." (PMID 33644047, 2021). "Some research has even analysed the possibility of BMPER as a therapeutic target for several cardiovascular diseases, including pulmonary inflammation and injury and idiopathic pulmonary fibrosis." (PMID 31064821, 2019). "To gain insight into the role of BMPER in the progression of lung fibrosis, we next investigated if and how 5′-azacytidine treatment affects matrix production." (PMID 26442443, 2015). "Taken together, demethylation with 5′-azacytidine regulates BMPER expression and reduces lung fibrosis in mice in vivo." (PMID 26442443, 2015). "5′-azacytidine treatment additionally regulated BMPER expression and reduced lung fibrosis in mice in vivo." (PMID 26442443, 2015). "We further demonstrated that the demethylation agent 5′-azacytidine regulated BMPER expression through the transcriptional level in vitro and attenuated lung fibrosis in mice in vivo." (PMID 26442443, 2015). "Demethylation with 5′-azacytidine treatment resulted in decreased BMPER expression in primary lung fibroblasts, attenuated fibroblast activation in vitro and lung fibrosis in vivo." (PMID 26442443, 2015). "Notably, BMPER promotes epithelial-mesenchymal transdifferentiation for heart cushions and participates in fibroblast activation and pulmonary fibrosis, indicating its function in fibrogenesis." (PMID 33644047, 2021). "BMPER mediates lung fibroblast activation in vitro and lung fibrosis in mice in vivo." (PMID 33644047, 2021). "Our studies demonstrated the profibrotic role of BMPER in pulmonary fibrosis." (PMID 26442443, 2015). "Furthermore, BMPER regulated lung fibrosis through TGF-β/BMP signaling." (PMID 26442443, 2015). "Therefore, further investigation into the mechanisms under which BMPER regulates lung fibrosis could provide a novel target for the development of therapeutics for patients with pulmonary fibrosis." (PMID 26442443, 2015). "In vivo experiment, we saw that global demethylation with 5′-azacytidine decreased the expression of BMPER and extracellular matrix, but did not completely abrogate lung fibrosis following bleomycin-induced lung fibrosis in mice." (PMID 26442443, 2015). "However, the role of BMPER in lung fibrosis has not been investigated." (PMID 26442443, 2015). "BMPER is a secreted glycoprotein that binds directly to BMPs and may regulate TGF-β/BMP signaling, but its role in lung fibrosis is not clear." (PMID 26442443, 2015).
ovarian carcinoma (4 papers, 2020 to 2024). A malignant neoplasm originating from the surface ovarian epithelium. "Previous studies have linked BMPER to lung cancer and ovarian cancer, and it has been shown that BMPER expression is controlled by methylation at the transcriptional level." (PMID 38244582, 2024). "This study demonstrates for the first time that BMPER is highly expressed in ovarian cancer and is an independent risk factor for prognosis." (PMID 32309430, 2020). "Because BMPER is over expressed in ovarian cancer tissues and cells, we have only performed BMPER knockdown experiments and conducted limited research on the molecular mechanism of pathways." (PMID 32309430, 2020). "After transfection of BMPER-specific siRNA into the ovarian cancer cell lines CAOV3 and OVCAR3, the changes in cell proliferation, migration, invasion, apoptosis, and cell cycle progression were further examined." (PMID 32309430, 2020). "The results of this study indicated that the percentages of positive and high BMPER expression in ovarian cancer were significantly higher than other ovarian tissues." (PMID 32309430, 2020). "In the follow-up studies, we will continue improving the experiment and further study the molecular regulatory mechanism of BMPER on ovarian cancer." (PMID 32309430, 2020). "Our results also showed that the inhibition of BMPER expression reduced the proliferation, migration, and invasion of ovarian cancer cell lines CAOV3 and OVCAR3." (PMID 32309430, 2020). "The expression levels of BMPER in four ovarian cancer cell lines CAOV3, OVCAR3, SKOV3, and ES-2 were detected by real-time PCR and Western blot." (PMID 32309430, 2020). "Inhibition of BMPER inhibited the proliferation, invasion, and migration of ovarian cancer cells and promoted apoptosis." (PMID 32309430, 2020). "BMPER may play important roles in the occurrence and progression of ovarian cancer as both a potential prognostic marker and as a new strategy for the treatment of ovarian cancer." (PMID 32309430, 2020). "BMPER expression in ovarian cancer cell lines was inhibited via RNA interference." (PMID 32309430, 2020). "This study confirmed for the first time that BMPER could affect the malignant biological behavior of ovarian cancer cells through the MAPK signaling pathway." (PMID 32309430, 2020). "In addition, the expression level of autophagy-related molecules was found changed after the inhibition of BMPER expression, which affected the autophagy of ovarian cancer cells." (PMID 32309430, 2020). "Although BMPER expression in ES-2 cells is relatively lower than that in other ovarian cancer cells, BMPER may still play a role in promoting the malignant biological behaviors such as invasion and migration of ES-2 cells." (PMID 32309430, 2020). "However, the current results of immunohistochemistry, cellular biological experiments, and pathway mechanism after knockdown of BMPER expression have important value in clarifying the role of BMPER in ovarian cancer." (PMID 32309430, 2020). "Our findings indicated that BMPER is closely related to poor prognosis in ovarian cancer." (PMID 32309430, 2020). "In that study, the researchers considered that BMPER may become a potential prognostic marker and that modification of this pathway may change the role of BMPER in promoting the malignant biological behavior of ovarian cancer cells." (PMID 33339178, 2020). "Previous studies showed that BMPER, CXCL10, and HOXA9 promote tumor angiogenesis and tumorigenesis in lung cancer, colon cancer, basal cell carcinoma, ovarian cancer, and liver tumor." (PMID 32432046, 2020). "Our team used a gene chip to find that BMPER expression was related to the expression of tumor biomarker human epididymis protein 4, but the role and mechanism of BMPER in ovarian cancer has not been reported." (PMID 32309430, 2020). "Currently, no reports have indicated the role of BMPER in ovarian cancer." (PMID 32309430, 2020). "No studies have investigated the role of BMPER in ovarian cancer." (PMID 32309430, 2020).
Alzheimer disease (2 papers, 2021 to 2022). A progressive, neurodegenerative disease characterized by loss of function and death of nerve cells in several areas of the brain leading to loss of cognitive function such as memory and language. "For example, BMPER has been associated with aging and its related diseases, such as Alzheimer's disease, and it is also involved in the regulation of the proinflammatory phenotype of the endothelium, functioning primarily in the vascular and respiratory systems." (PMID 33657282, 2021). "In previous GWAS, associations were reported between BMPER and FVC, FEV1, and other chronic diseases such as Alzheimer’s disease and metastatic colorectal cancer." (PMID 35624665, 2022).
atherosclerosis (2 papers, 2018 to 2019). A disease characterized by the build-up of fatty material and calcium deposition in the arterial wall resulting in partial or complete occlusion of the arterial lumen. "In recent years, BMPER has become of increasing interest in EC biology, including its role in cell inflammation, atherosclerosis and angiogenesis." (PMID 31064821, 2019).
B-cell lymphoma (2 papers, 2014 to 2020). "The gene promoters of BMPER, CDH1 and LRP12 were methylated in all analyzed B-cell lymphoma cell lines across all subtypes." (PMID 25226156, 2014). "We focused on major types of B-cell lymphoma (BL, DLBCL ABC, DLBCL GCB, FL and PMBL) and demonstrated that the gene promoters of LRP12 (94%), CDH1 (92%), and BMPER (58%) were methylated at a high frequency, whereas DUSP4 and BMP7 showed lower methylation frequencies (32% and 22%, respectively)." (PMID 25226156, 2014).
craniosynostosis (2 papers, 2024 to 2025). Craniosynostosis is defined as the premature fusion of one or more cranial sutures leading to secondary distortion of skull shape resulting in skull deformities with a variable presentation. "In fact, GWASs on non-syndromic craniosynostosis have identified risk SNPs near BMP2, BMP7, BMPER, and DLX5, which overlap with loci identified here, and are directly linked to RUNX26,111–115." (PMID 40087503, 2025).
hyperglycaemia (2 papers, 2021 to 2025). "More importantly, the delivery of BMPER recombinant protein or its adeno-associated viral (AAV) particles dramatically alleviates insulin resistance and hyperglycemia in diabetic mice." (PMID 33772019, 2021). "Here, the authors identify a crucial role for endothelial BMPER function in glucose homeostasis, and BMPER overexpression was shown to alleviate insulin resistance and hyperglycemia in diabetic mice." (PMID 33772019, 2021). "Previous studies have indicated that overexpression of BMPER or the delivery of recombinant BMPER protein can alleviate insulin resistance and hyperglycaemia in diabetic mice, suggesting the protective role of BMPER in glucose homeostasis, making this a possible therapeutic target." (PMID 40569436, 2025). "The inhibitory impact of AGEs on BMPER protein level, but not its mRNA level, suggests that some transcription-independent mechanisms might be also involved for the regulation of BMPER protein by hyperglycemia." (PMID 33772019, 2021).
Hyperinsulinemia (2 papers, 2021 to 2023). An increased concentration of insulin in the blood. "Both whole-body and EC-specific BMPER inducible knockout (iKO) mice display similar glucose defects, including hyperinsulinemia, insulin resistance, and glucose intolerance, suggesting vascular endothelium plays a causal role in glucose homeostasis through secreting metabolic regulators." (PMID 33772019, 2021). "Since BMPER serum level was lower in BMPER iKO mice that spontaneously developed hyperinsulinemia and insulin resistance, we examined whether there is an association between BMPER level and insulin resistance." (PMID 33772019, 2021). "Interestingly, BMPER iKO mice displayed hyperinsulinemia and higher homeostasis model assessment for insulin resistance (HOMA-IR) scores than WT mice at four months after tamoxifen injection." (PMID 33772019, 2021). "Both global and endothelial cell-specific inducible knockout of BMPER cause hyperinsulinemia, glucose intolerance and insulin resistance without increasing inflammation in metabolic tissues in mice." (PMID 33772019, 2021). "Following the injection of recombinant BMPER into HFD-fed mice, we detected significant normalization of hyperinsulinemia and improved glucose and insulin tolerance responses." (PMID 33772019, 2021). "Given that BMPER iKO mice spontaneously developed hyperinsulinemia, insulin resistance, and glucose intolerance without weight gain, we hypothesized BMPER iKO mice are more sensitive to the metabolic effects of high-fat diet (HFD)." (PMID 33772019, 2021).
Insulin resistance (2 papers, 2021 to 2025). Increased resistance towards insulin, that is, diminished effectiveness of insulin in reducing blood glucose levels. "In addition, BMPER levels negatively correlated with body weight and plasma levels of insulin and TGs, suggesting an association between decreased BMPER levels and conventional serum markers of insulin resistance." (PMID 33772019, 2021). "BMPER depletion in ECs also resulted in hepatic and peripheral insulin resistance, indicated by clamp and insulin signaling studies." (PMID 33772019, 2021). "However, BMPER iKO mice exhibited more severe glucose intolerance and insulin resistance than WT mice." (PMID 33772019, 2021). "In summary, our data unravel an unexpected role for BMPER in glucose homeostasis and indicate BMPER supplementation (i.e., gene therapy or recombinant protein delivery) can be a potential approach to treat T2DM and insulin resistance." (PMID 33772019, 2021). "Here, our data indicate BMPER is downregulated in humans with metabolic syndrome and DIO mice, suggesting endothelial secretory function might also be disrupted during metabolic stress conditions and contribute to the progression of T2DM and insulin resistance." (PMID 33772019, 2021).
type 1 diabetes (2 papers, 2015 to 2025). "We identified a variant, rs10232170, in BMPER as a possible novel type 1 diabetes locus (p=9.897×10−9)." (PMID 40569436, 2025). "Furthermore, BMPER mRNA levels were increased in aortas of STZ-induced type I diabetic mice by 2.5-fold (P < 0.05)." (PMID 26264461, 2015).
alcoholism (1 paper, 2017). "While many identified genes were generally in alignment with prior knowledge, further work should be done to understand the associations between alcoholism and the five genes that went uncorroborated in the literature (BLNK, BMPER, PDLIM5, VEPH1, AMPD3)." (PMID 28361705, 2017).